IL6 (interleukin 6)
Diseases named in the same sentence as IL6 in open-access papers (continued):
Sharing a sentence is not in itself a finding about the gene and the disease.
Sepsis (continued). "There is abundant precedent for targeting IL-6 or its soluble receptor to ablate pathologic cytokine release cascades associated with rheumatoid arthritis, adoptive immunotherapy, or infectious disease and sepsis." (PMID 39114667, 2024). "Our study indicates that sTREM-1, lactate, and IL-6 are closely associated with sepsis severity and may serve as early predictive biomarkers for unfavorable prognosis." (PMID 39655134, 2024). "Researchers are investigating new biomarkers such as interleukin-6 (IL-6) and soluble triggering receptor expressed on myeloid cells-1 (sTREM-1) for their potential as diagnostic and prognostic indicators in sepsis, offering hope for improved early detection and outcomes in adult populations." (PMID 39655134, 2024). "A previous study on pediatric patients assessed the diagnostic value of IL-6 and sTREM-1 in sepsis." (PMID 39655134, 2024). "Early blockage of IL-6 by tocilizumab in children with severe sepsis/septic shock could reduce the risk of the development of multiple organ failure and increase the survival outcome." (PMID 38672594, 2024). "IL-6 and lactate, in particular, exhibited the strongest correlations with sTREM-1, especially after applying a logarithmic transformation, indicating a more pronounced relationship with sepsis risk." (PMID 39655134, 2024). "Despite there is not an ideal-specific biomarker, the simultaneous detection of biomarkers with different behavior during an infection such as procalcitonin (PCT) as high specificity biomarker with one of the earliest biomarkers in sepsis as interleukin-6 (IL-6) increases diagnostic performance." (PMID 38240873, 2024). "IL-6 serves as an important mediator during the acute phase of response to inflammation in sepsis, which is considered a biomarker with high diagnostic and prognostic value in sepsis." (PMID 38994336, 2024). "Human chorionic gonadotropin, a hormone first identified in the placenta, can reduce the expression of pro-inflammatory mediators (TNF-α, IL-6, and Pentraxin 3) and chemokines (macrophage inflammatory protein 1-a and chemotokine ligand 5) caused by sepsis, and improve organ damage caused by sepsis." (PMID 37629199, 2023). "In this work, attempts were made to identify a diagnostic marker for pediatric sepsis, and the impact of immune cell infiltration on pediatric sepsis was investigated (e.g., coagulation, complement, IL6-JAK-STAT3 signaling, inflammatory response and TNFα signaling via NFκB)." (PMID 37115484, 2023). "Macrophages can recognize LPS released by Gram-negative bacteria through TLRs, leading to excessive expression of inflammatory factors, including IL-1β, TNF-α, and IL-6, which are considered the leading cause of multiple organ dysfunction in the early stage of sepsis." (PMID 37840694, 2023). "Additionally, IL-6 (174G/C) polymorphism was proved to be associated with an increased susceptibility to sepsis." (PMID 37388447, 2023). "In our study cohort, high levels of IL-6 and IL-10 at the onset of sepsis (day of study inclusion) were significantly associated with the 30-day mortality as could be expected based on the literature." (PMID 37907989, 2023). "Regarding the inflammatory markers selected for this study, IL-6 was chosen for its well-established role as a primary pro-inflammatory cytokine and its recognized association with neonatal complications, such as sepsis, necrotizing enterocolitis, and even ROP." (PMID 37371000, 2023). "Results of conventional meta-analysis showed that IL-8 manifested the highest pooled sensitivity and specificity in the detection of early-onset sepsis in neonates, which indicates the superior diagnostic properties of IL-8 for neonates as compared to IL-6, IL-8, IL-10." (PMID 38027268, 2023). "Thereby, Ruxolitinib could be suitable to prevent sepsis-associated IL-6 release to impede EC dysfunction via promoting RNase1 expression." (PMID 37189117, 2023).
Sepsis (continued). "IL-6 has a moderate diagnostic AUC value of 0.81 (95% CI, 0.78–0.85) in critically ill patients with suspected infection, whereas it has a lower diagnostic AUC value of 0.77 (95% CI, 0.73–0.80) in patients with sepsis." (PMID 37592204, 2023). "However, markedly rising IL-6, to the degree of >1000 pg/mL, can also be associated with secondary infections and sepsis." (PMID 36983429, 2023). "Several studies have detected nucleotide changes in the gene that codes for IL-6, which generates polymorphisms that may be related to risk factors or protectors to developing sepsis, septic shock, and even death." (PMID 37887780, 2023). "Notably, deficiency of Plg led to an overall worse sepsis outcome, which was accompanied by elevated levels of IL-6 when compared with Plg-sufficient mice." (PMID 36917195, 2023). "In addition, the study found that subjects with IL-10-1082 AA and IL-6-174 CC genotypes had a higher risk of sepsis and increased mRNA levels." (PMID 37753078, 2023). "Notably, increased IL-6 systemic levels were associated with severe inflammatory response in patients with sepsis and have an important predictive role as a multiple-organ dysfunction biomarker." (PMID 37999381, 2023). "According to our results, when used in addition to routine blood tests, IL-6 and IL-2 can improve overall diagnostic ability in predicting BI, while IL-10 could increase specificity in early sepsis recognition." (PMID 35582414, 2022). "Interestingly, increased circulating levels of TNF-α and IL-6 are considered the main features of the inflammatory response associated with sepsis and play a key role in the pathophysiology of severe sepsis." (PMID 35163089, 2022). "IL-6 is one of the most consistently elevated inflammatory mediators in burn patients, and its high levels on the first day after injury increase the risk of developing sepsis." (PMID 35054900, 2022). "In addition to sepsis and upregulation of pro-inflammatory cytokine (IL-6, IL-1ß, and TNF-α) production, the association of miR-192-5p with regulation of the miR-192-5p–X-linked inhibitor of apoptosis axis in this condition has been investigated in animals." (PMID 35305556, 2022). "Four cytokines, TNF-α, IL-1β, IL-6, and IL-8 have been most strongly associated with sepsis." (PMID 35563475, 2022). "Similar to our results, a previous study on the risk factors of sepsis showed that pre-operative IL-6 levels could predict the incidence of sepsis." (PMID 36299462, 2022). "In both control and OVR females, sepsis increased the myocardial expression of genes encoding protein associated to inflammation, interleukin-6 (IL-6), IL-10 and IL-18, to cell cycle and survival, Janus Kinase 2 (JAK2) and signal transducer and activator of transcription 3 (STAT3)." (PMID 35322092, 2022). "We speculated that the high expression of proinflammatory cytokines (Il1β, Il6, Il8, and Tnf-α) in lung might be the main cause of respiratory inflammation and septicemia." (PMID 36447208, 2022). "The following infection indexes were selected: procalcitonin is a specific index of severe bacterial inflammation and fungal infection and is associated with sepsis; limulus test for endotoxins indicates is used to reflect G-bacterial infection; IL-6 is an index that reflects early infection." (PMID 35844449, 2022). "However, a recent comparison of MIS-C and sepsis patients questioned the utility of IL-6 in diagnosis and risk stratification by demonstrating much higher IL-6 levels in sepsis than in children with critical MIS-C." (PMID 36148243, 2022). "Several studies have also reported that the serum IL-6 concentration is associated with disease severity, organ dysfunction, and overall mortality among patients with sepsis, burn and trauma injuries, and cardiovascular diseases, as well as those undergoing hemodialysis." (PMID 36005726, 2022).
Sepsis (continued). "In healthy adults the level of IL-6 is normally in the range of 5–25 pg/mL, whereas higher levels (e.g., up to 1,000 pg/mL) of IL-6 in serum or blood can be associated with the abnormal physical conditions including sepsis or cancer." (PMID 34900966, 2021). "Similarly, IL-6 overexpression has been associated with more severe sepsis and worse outcomes, potentially due to complement activation." (PMID 34485339, 2021). "For example, IL-6 and IL-8 were, both individually and as part of a multibiomarker score, associated with 28-day nonsurvival in a small Spanish cohort of patients with severe sepsis or septic shock." (PMID 32034914, 2021). "The immune response to infective agents may trigger a cascade of cytokines like interleukin-6 (IL-6), causing cells impairment, organs failure, and ultimately result in the coagulopathy, which is significantly correlated to the prognosis of sepsis patients." (PMID 33446739, 2021). "We found 15 articles reporting the diagnostic value of IL-6 for sepsis." (PMID 33902476, 2021). "Additionally, L.m.-induced septic death and sepsis-associated comorbidities (hypothermia, systemic IL-6 surge) were significantly attenuated by the transfer of NPD1-primed WT pMΦ in both WT and Gpr37−/− mice." (PMID 33731716, 2021). "Accordingly, combining NLR with IL-6 might potentially enhance the ability to predict the death risk of patients with sepsis." (PMID 33796105, 2021). "The sensitivity, specificity, and AUC of IL-27 in our study showed similarities with PCT (0.77, 0.79, and 0.85, respectively), IL-6 (0.73, 0.76, and 0.81, respectively), and presepsin (0.77, 0.73, and 0.86, respectively), which are valuable diagnostic markers for sepsis in published studies." (PMID 33954170, 2021). "NFKBIA gene was iterated in 9 out of the 10 top pathways, MYD88 gene was enriched in 3 pathways, and IRAK4 was the only gene located on chromosome X. Their diagnostic accuracy was compared to IL6, which is used in our hospital protocol as a gold standard test for inflammatory reaction in sepsis." (PMID 34183713, 2021). "Although IL-6 is a useful biomarker and diagnostic indicator of sepsis progression, the administration of anti-IL-6 or anti-IL-6R therapy for the treatment of sepsis has not been studied because IL-6 is an important factor driving immune activation as a host defense against infection." (PMID 34253862, 2021). "IL-6, PCT and CRP at onset of sepsis were associated with various clinical measures of sepsis severity, such as need for inotropic support and mechanical ventilation, with IL-6 and PCT showing the strongest associations, with a higher discriminative value compared to CRP." (PMID 33407770, 2021). "In our collective, patients suffering from postoperative sepsis were characterized by high plasma levels of both pro-inflammatory IL-6 and anti-inflammatory IL-10 at the time of study inclusion, markers associated with disease severity and clinical outcome in sepsis." (PMID 33939725, 2021). "However, low level of different sepsis-associated metabolites in patients 2 indicated the presence of moderate inflammation which was confirmed by the level of IL-6 < 25 pg/mL." (PMID 33672777, 2021). "Finally, we assessed the production of IL‐6, an inflammatory mediator important in the pathobiology of sepsis with higher levels associated with worse clinical outcome." (PMID 33438259, 2021). "The G allele of rs1800795 promotes higher circulating levels of IL-6 in patients with sepsis." (PMID 32070384, 2020). "Toxic neutrophil changes, serum amyloid-A (SAA), and selected cytokines including TNF and IL-6 have been described as potential diagnostic and prognostic biomarkers in cats with sepsis, but independent evaluation of these biomarkers in a large population of septic cats is currently lacking." (PMID 32548135, 2020). "It has been established that blood levels of IL-6 had a diagnostic value and could predict the treatment success in sepsis." (PMID 32695814, 2020).
Sepsis (continued). "Next, we tested if a combination of MRproADM with established and routinely used markers such as CRP, PCT, and IL6 could increase the diagnostic accuracy for sepsis using a composite score." (PMID 32831638, 2020). "Lnc‐MALAT1 was positively correlated with Scr (r = .254, P < .001), CRP (r = .494, P < .001), TNF‐α (r = .387, P < .001), IL‐1β (r = .330, P < .001), IL‐6 (r = .431, P < .001), and IL‐8 (r = .420, P < .001), while negatively associated with albumin (r = −.153, P = .033) in sepsis patients." (PMID 32309886, 2020). "Additionally, increased IL-6 concentrations correlate with the risk of death in sepsis in humans and dogs." (PMID 32548135, 2020). "However, it has been shown that decreasing IL-6 levels are associated with a protective effect in pneumococcal septicemia in pigs." (PMID 31947746, 2020). "Moreover, excessive secretion of IL‐6 causes cellular injury during sepsis (Tanaka, Narazaki, & Kishimoto, 2014)." (PMID 32497259, 2020). "Raised serum levels of IL-6 have been associated with sepsis in AKI patients." (PMID 32487191, 2020). "However, it was soon realised that IL-6 is involved in a different inflammatory cascade in response to exercise than sepsis (a life-threatening condition caused by a dysregulated host response to infection)." (PMID 32722013, 2020). "TNF-α and IL-6 are the primary mediators of sepsis, which can cause septic shock." (PMID 33042031, 2020). "A study found that IL-6-174 G allele was associated with early-onset sepsis in Saudi infants." (PMID 30782124, 2019). "We hypothesized that higher IL-6 level induced by C allele could be more sensitive in very young persons and lead to aggravation of sepsis." (PMID 30782124, 2019). "This suggested that IL-6 -174G/C polymorphism was distributed in Asians that resided in certain areas and might have an influence on the pathogenesis of sepsis." (PMID 30782124, 2019). "Another proinflammatory cytokine, IL-6, has a high predictive value for death caused by sepsis." (PMID 30949497, 2019). "A recent study showed that PTX3 discriminated sepsis and septic shock patients from controls in a medical intensive care unit (ICU) in accordance with the Sepsis-3 definitions, suggesting that PTX3 has a diagnostic value comparable to that of IL-6 in sepsis and septic shock." (PMID 31718563, 2019). "However, two studies included in our analysis reported possible association between IL-6 -174G/C polymorphism and the risk of sepsis in the Chinese Han population in Henan province." (PMID 30782124, 2019). "Furthermore, IL-6 was an independent risk factor for 28-day mortality in patients with sepsis and septic shock." (PMID 31718563, 2019). "Although previous report has proved that IL-6 is the main factor stimulating the expression of hepcidin through the STAT3 signaling pathway in patients with septicemia and burns, the high level of hepcidin mRNA is also observed in IL-6-deficient mice with chronic inflammation." (PMID 31814801, 2019). "Although previous study has proved that IL-6 is the main factor stimulating the expression of hepcidin through the STAT3 signaling pathway in patients with septicemia and burns and that the high level of hepcidin mRNA is also observed in IL-6-deficient mice with chronic inflammation." (PMID 31814801, 2019). "Prior studies of polymicrobial sepsis have shown that under conditions of Zn deficiency, the inability to supress NF-κβ activation leads to overproduction of the pro-inflammatory cytokines IL-1β and IL-6, resulting in septic shock." (PMID 31437249, 2019). "Similarly, PTX3 in combination with IL-6 improved the risk stratification of patients with sepsis or septic shock as classified using the updated sepsis-3 definition." (PMID 31031772, 2019). "However, only the IL-6 level was closely associated with the rs153109 polymorphism in patients with sepsis." (PMID 30268141, 2018).
Sepsis (continued). "Increased circulating levels of both pro-inflammatory (IL-6) and anti-inflammatory (IL-10) mediators have been associated with poor survival in numerous studies in patients with sepsis, including patients with septic shock randomized to different fluid resuscitation strategies." (PMID 29728790, 2018). "Recent data have suggested that stimulation of primed macrophages with purified M proteins may promote inflammasome activation and secretion of IL-1β, which together with IL-6 and TNFα is implicated as a key mediator of sepsis." (PMID 29579113, 2018). "In addition, significantly increased levels of IL-6, which have been associated to the severity of sepsis in humans and animal models, were found in serum 4 h post-inoculation." (PMID 30123776, 2018). "Furthermore, previous studies have demonstrated that IL-6 is a crucial cytokine in the pathophysiology of severe sepsis and that increased levels of IL-6 are related with the highest risk of death in sepsis patients." (PMID 30513815, 2018). "However, increases in IL-6, IL-8 and TNFα are also associated with a wide variety of immune activity like acute-phase response (e.g. sepsis and viral infections) and autoimmunity which also can be related to schizophrenia." (PMID 28923068, 2017). "Among these genetic variations, the SNPs at IL-6 promoter are important members which might be associated with sepsis risk and death." (PMID 28247301, 2017). "Although mediators such as IL-8 and IL-6 have been evaluated in febrile neutropenic children as risk markers for severe infections, the kinetics of cytokines during the time of fever or occurrence of sepsis has been rarely studied." (PMID 28769538, 2017). "Furthermore, the rs1800795 IL-6 polymorphism has been associated with the risk of sepsis and death, but with different results depending on the study." (PMID 28247301, 2017). "IL-6 is a proinflammatory cytokine which plays a vital role in the regulation of host immune response in sepsis, and elevated expression of IL-6 is associated with the development of severe sepsis and mortality." (PMID 28247301, 2017). "Novel biomarkers such as PTX-3 in combination with established ones such as IL-6 might improve the individual time-dependent risk-stratification of patients with sepsis or septic shock." (PMID 28793880, 2017). "The activation of macrophages by the stimulation of the TLR4 ligand leads to the production of several inflammatory mediators, including TNF, IL-1β and IL-6, that contribute to the inflammatory response to defend pathogenic infection, but also associate with the severity of sepsis." (PMID 28593998, 2017). "IL-6 has also been used as a prognostic marker for outcomes in septic patients, but it is still unknown whether sepsis-induced mitochondria dysfunction is associated with the production of IL-6." (PMID 28549777, 2017). "IL-6 has been used as a prognostic marker for outcomes in severe septic patients, but it is still unknown whether sepsis-induced mitochondria dysfunction is associated with the production of IL-6." (PMID 28549777, 2017). "Similarly, in a mouse sepsis model, IL-6 was found to be associated with increased mortality and increased lung complement 5a receptor expression." (PMID 26949510, 2016). "In the “20 %” group, we confirmed the presence of sepsis associated with hypotension below 65 mmHg, pro-inflammatory balance with high IL-6 levels and augmented IL-6/IL-10 ratio, organ dysfunction, hyperlactatemia, elevated serum creatinine, and hepatocyte centrilobular necrosis." (PMID 27430881, 2016). "IL-6 and IL-8 are inflammatory markers most strongly associated with severity of sepsis and death." (PMID 27431667, 2016). "Similarly, ATF3 induced by reactive oxygen species causes high susceptibility to secondary infections by repressing interleukin 6 (IL-6) expression during sepsis-associated immunosuppression." (PMID 27146783, 2016).